Y_RNA (Y RNA )
Gene: Miscellaneous RNA gene on chromosome 17 (28,834,722 to 28,834,822, forward strand). Ensembl gene ENSG00000238516.
Homologues: Orthologues: chimpanzee Y_RNA (97% identical). Paralogues in human: RNY3 (88% identical), Y_RNA (88% identical), Y_RNA (87% identical), Y_RNA (86% identical), RNY3P1 (85% identical), Y_RNA (85% identical), RNY3P16 (84% identical), Y_RNA (84% identical), RNY3P14 (83% identical), Y_RNA (83% identical), RNY3P9 (82% identical), Y_RNA (82% identical), and 93 more.